Y_RNA (Y RNA )
Gene: Miscellaneous RNA gene on chromosome 9 (12,885,321 to 12,885,417, forward strand). Ensembl gene ENSG00000222658.
Homologues: Orthologues: chimpanzee Y_RNA (100% identical). Paralogues in human: RNY4P7 (81% identical), RNY4 (80% identical), RNY4P3 (80% identical), Y_RNA (80% identical), Y_RNA (79% identical), RNY4P10 (78% identical), RNY4P14 (78% identical), RNY4P17 (78% identical), RNY4P25 (78% identical), RNY4P28 (78% identical), RNY4P6 (78% identical), Y_RNA (78% identical), and 92 more.